IFNB1 (interferon beta 1)
Diseases named in the same sentence as IFNB1 in open-access papers (continued):
Sharing a sentence is not in itself a finding about the gene and the disease.
infection (continued). "Measurement of viral ORF1A RNA by reverse transcription quantitative PCR (RT-qPCR) was used to assess the levels of viral transcripts 24 and 48 hours after infection, whereas IL6 and IFNB1 mRNA levels were measured to assess the concomitant induction of cytokines." (PMID 36264642, 2022). "In particular, the S. Typhimurium-induced Ifnb1 expression was attenuated in cGAS−/− or STING−/− PMs from 2 h.p.i, suggesting the cGAS-STING pathway was also involved in the initial activation of type I IFN response during infection." (PMID 35604097, 2022). "For example, heat-iMVA infection triggered higher levels of IFN-inducible genes than MVA, including Ifih1 (MDA5), Ddx58 (RIG-1), Oasl2, Oas3, TLR3, Nod1, Ifna4, Ifnb1, Ccl5, Cxcl9, Cxcl10, and members of the guanylate binding protein (Gbp) family, as largely dependent on STING (marked as b)." (PMID 36261460, 2022). "Analysis of interferons (IFNs) and IFN stimulated genes (ISGs) 24 h post-HRV16 infection revealed induction of IFNB1 and IFNL1 genes by HRV16 but not UV-HRV16." (PMID 36366528, 2022). "In addition, aged ferrets showed high expression of chemokines (CCL4 and CXCL10) and inflammatory cytokines (IFNB1, IL1B, IL6, and IL7) in the early phase of infection." (PMID 35013229, 2022). "Specifically, infection of MAGI1-null ECs with IAV upregulates expression of signal transducer and activator of transcription 1 (STAT1), interferon b1 (IFNb1), myxovirus resistance protein 1 (MX1) and 2′-5′-oligoadenylate synthetase 2 (OAS2), and activate STAT5." (PMID 36082118, 2022). "IL-33 concentration dependently increased IFNB1 in the absence of infection while in the presence of both IL-33 and HRV16 there was a further significant increase in expression of IFNB1 and IFNLI." (PMID 36366528, 2022). "As expected, Ifnb1 was expressed only during infection with cytosolic, wild-type L. monocytogenes in both cell subsets, where Il1b was induced by TLR signaling during infection with both wild-type and Δhly L. monocytogenes infection." (PMID 34555127, 2021). "We observed an increased abundance of Ifnb1 mRNA levels in all of the four Mycobacterial species (log2FC, M. kansasii: 7.1; M. riyadhense:5.3; M. tuberclosis:8.2; M. bovis BCG:7.4) at 3 hours post infection." (PMID 34396095, 2021). "Inconsistent with the observed trend in the IFNB1 level, persistent upregulation of numerous ISGs, including CXCL10, MX1, and ISG15, was observed in response to SARS-CoV-2 infection from 3 to 7 days post-infection." (PMID 34104087, 2021). "We observed increased IFNB1, IL29/IFNL1, IL28A/IFNL2, IFNL3, RSAD2, and CXCL10 post infection." (PMID 33409274, 2020). "In these experiments, TRIM5 knockout THP-1 cells expressed reduced IFNB1 under basal conditions and IFNB1 expression was not increased in response to HIV-1 CA P90A infection." (PMID 33052966, 2020). "Whereas infection of control THP-1 macrophages with HIV-1 CA P90A increases the expression of IFNB1, this effect is not seen in ULK1, BECN1, or ATG7 knockout THP-1 cells." (PMID 33052966, 2020). "The variant was a cis-eQTL for IFNB1 after activation of the TLR1/TLR2, TLR4, and TLR7/TLR8 pathways, but not after infection with an influenza virus." (PMID 33147208, 2020). "By contrast, HMGB2-depletion had no detectable impact on IFNB1 accumulation induced in response to infection with VSV, an RNA virus, in agreement with reports showing HMGB2 was dispensable for IFNB1 induction by RNA in murine cells." (PMID 31841110, 2019). "Ifnb1 and Ifna4 are unusual amongst type I IFN genes as their expression is induced early in response to infection in an IFN protein-independent manner, although this may be cell type dependent." (PMID 31076606, 2019). "qPCR analysis indicated that induction of antiviral genes including IFNB1, ISG56 and CXCL10 following infection with the DNA viruses HCMV, herpes simplex virus 1 (HSV-1), and vaccinia virus (VACV) was inhibited in HFF-UL42 as compared to empty vector-transduced control cells (HFF-Vec)." (PMID 31107917, 2019).
infection (continued). "However, both the CA/04-NAK331N and CA/04-NAS79L,K331N viruses induced significantly lower levels of IFNB1, IFNL1, and IFNL2/3 gene expression at 48 and 72 h post-infection (P < 0.05)." (PMID 28750037, 2017). "We then confirmed that knockdown of the CD147 expression by miR-US25-1-5p could specifically reduce the activation of IFNB1 and interferon-related gene ISG15 and the NF-κB downstream genes IL-6 and TNF-α induced by HCMV early infection." (PMID 29194430, 2017). "Astrocytes infected or not with SIV/17E-Fr at a multiplicity of infection of 0.1 were then exposed or not to 100 units of recombinant macaque IFNB1 per milliliter of culture medium, creating four experimental conditions." (PMID 26936683, 2016). "Upon infection with WT EMCV, induction of Ifit1 and Ifnb1 was limited." (PMID 24550253, 2014). "More than 80% of cells have a small number of cytokines (black squares) in the same box at 6 hours post-infection because the IFNB1 gene has not been turned on in most infected cells; this number declines to zero by 9 hours." (PMID 24067165, 2013). "However, upon infection with the Sendai virus (SeV), the cells exhibited increased expression of IFN and chemokine genes (IFNB1, IL29, IL28A, IL28B and CXCL11) and interferon-stimulated genes (DDX58, IFIH1, DHX58, IFIT1-3, and OASL)." (PMID 20661427, 2010). "This includes most Ifna isoforms, Ifnl2, Ifnl3, Ifnb1, Tnf, and numerous other chemokines and cytokines representing the acute pDC anti-viral response that is absent in suppressed pDCs at later stages of infection." (PMID 39920132, 2025). "In addition, the expression of Ifnb1 and Cxcl10 was severely impaired, whereas EMCV replication was exacerbated in the brains or lungs of Lyz2‐Cre Usp8fl/fl mice compared with control littermates 48 h after EMCV infection." (PMID 40525588, 2025). "Also, upon SLAMF1 depletion, we observed reduced HMPV-N mRNA and protein levels at late time points of infection, which could suggest that SLAMF1 affects viral uptake or replication that could lead to altered IFNB1 expression." (PMID 41346628, 2025). "Following RSV-L19 infection (MOI = 10) of sh-ARCN1-RAW264.7 cells for 12 h, RT-qPCR analysis revealed significantly increased mRNA levels of Ifnb1 and interferon-stimulated genes Isg15 and Ifit1 compared to sh-NC-RAW264.7 controls, suggesting that ARCN1 suppresses RSV-induced IFN-β signaling." (PMID 41343552, 2025). "Intriguingly, while UL138 expression reduced IFNB1 and CXCL10 accumulation downstream of cGAS-STING-TBK1, it has also been reported to enhance the expression of some interferon stimulated genes (ISGs) at late times during productive infection, presumably by promoting the activation of STAT1." (PMID 38932169, 2024). "RT-qPCR did not reveal significant differences in the amount of TMEV RNA as well as Ifnb1, Isg15, Eif2ak1 (PKR), Tnfa, Il1a, Il1b, Il6, Il10, Il12 (p40) and Ifng transcript numbers in the brain of Asc−/− and Casp1−/− mice and their respective wild type littermates at 4 days after TMEV infection." (PMID 37414913, 2023). "Moreover, M35-mediated inhibition of Ifnb1 expression was observable both in the context of infection and upon ectopic expression of M35, implying that no further viral factors were required for M35’s immunomodulatory activity." (PMID 37289084, 2023). "Since we observed unaltered IFNB1 response to synthetic RNA and RNA viruses, RNA-sensing pathways appear to be largely intact, and it is therefore not surprising that the patient has not developed severe disease upon infection with RNA viruses." (PMID 37937644, 2023). "Furthermore, we observed that HRV-16 pre-infection with MOIs of 0.5 and 0.1 (but not 0.01) significantly boosted IFNB1 expression by AECs infected with SARS-CoV-2 WA-01 (MOI 0.5)." (PMID 35484173, 2022). "In vitro infection with VACV∆C7L failed to induce Ifnb1 gene expression in Clara cells." (PMID 35351885, 2022).
infection (continued). "Interestingly, I267L inhibited transcription of IFNB1 gene induced by infection of SeV, whose RNA is sensed by RIG-I, but not by HSV-1, whose DNA is mostly sensed by cGAS." (PMID 35089988, 2022). "In addition to LPS, the rs12553564 variant was found to be an eQTL for IFNB1 in monocytes activated by Pam3CSK4 (targeting the TLR1/TLR2 receptors) and R848 (targeting the TLR7/TLR8 receptors), but not after infection with an influenza virus." (PMID 33147208, 2020). "As depleting TIF-IA had no detectable impact on IFNB1 mRNA accumulation in response to infection with the RNA virus vesicular stomatitis virus (VSV), this suggested that rRNA biogenesis selectively influenced IFNB1 induction in response to viruses like HCMV with dsDNA genomes." (PMID 31841110, 2019). "In addition, UV-inactivated HCMV, which does not undergo viral transcription and translation after infection, induced higher levels of IFNB1, ISG56, and IL6 mRNA than un-treated HCMV." (PMID 31107917, 2019). "Infection of the human lung epithelial cell line A549 with RSV-HD resulted in the expression of IFNL1 (also known as IL-29), IFIT1 (also known as ISG56) and IFNB1; no expression of these genes was detected upon infection with RSV-LD, despite higher levels of viral replication (RSV G expression)." (PMID 26336095, 2015). "The Ifnb1 and Il13ra1 genes were not significantly differentially expressed compared to the uninfected pooled common reference at any of the time-points following H37Rv-infection." (PMID 22039457, 2011). "However, close inspection of the data shows evidence for an initial and small first phase of IFNB1 induction that begins as early as 1 hour after infection and never reaches levels above 1% of maximum until the sizeable induction observed after 6 hours." (PMID 21347441, 2011). "However, most IFN-β expressing IMs were not infected with Mtb, and most infected IMs were not Ifnb1 or reporter positive, indicating direct infection is insufficient and may not be the main driver of type I IFN expression in vivo." (PMID 38029747, 2023). "By contrast, the Ifih1−/−Sting1gt/gt AECII failed to induce Ifnb1, Ccl4, and Ccl5 gene expression and to produce IFN-β, CCL4 and CCL5 upon VACV∆C7L infection." (PMID 35351885, 2022). "Knockout of LUC7L2 significantly potentiated transcription of downstream antiviral genes such as IFNB1 and ISG56 induced by infection of the DNA virus HSV-1 but not the RNA virus Sendai virus (SeV)." (PMID 34155193, 2021). "The induction of IFNB1 and IFNL1 expression was readily observed in SARS-CoV-2–infected tissues at 37°C, with no significant change observed during infection at 40°C relative to mock-treated samples." (PMID 34932557, 2021). "Upon in vitro infection with ZIKVBR, a marked induction of mRNA expression of IFNB1, IFNL1, IFNL2 and IFNL3 genes but not of IFNE was observed." (PMID 32745093, 2020). "qPCR analysis indicated that knockdown of UL42 promoted HCMV- but not HSV-1-induced transcription of IFNB1, ISG56, ISG54, CXCL10, and IL6 genes at 6, 12, and 24 hr post-infection in HFFs." (PMID 31107917, 2019). "We initially tested the possible role of acetate in IFN-β production and found increased expression of Ifnb1, but not Ifna1, in the lung of RSV-infected mice treated with acetate compared to untreated RSV-infected mice 3 and 5 days after infection." (PMID 31332169, 2019). "Specifically, on day 1 after infection, no SARS-CoV-2-mediated induction of IFNB1 was observed." (PMID 34104087, 2021). "However, the infection of NHBE cells with SARS-CoV-2 failed to induce the expression of I-IFNs, including IFNB1 and a series of IFN genes, as supported by the quantitative results for all protein-coding transcripts." (PMID 34104087, 2021).
tumor (865 papers, 2002 to 2026). "To directly confirm that adaptive immunity is essential for effective tumor control, we created another heterogeneous mixture of cancer cells expressing IFNB1 or GM-CSF." (PMID 40282455, 2025). "While F4/80+ TAMs or viable tumor regions showed negligible Ifnb1 expression, the most prominent signal was localized to regions of necrosis, suggesting a nonimmune, damage-associated origin." (PMID 40627458, 2025). "The mixed population co-expressing GM-CSF and IFNB1 exhibited significantly faster tumor regression compared to the population with only IFNB1 expression." (PMID 40282455, 2025). "We observed significant upregulation of the transcriptional levels of Ifnb1, Ifit1, Ifit2, Ifit3, Irf7, and Mx1 in irradiated 4T1 tumor tissues and irradiated CT26, H22, and GL261 carcinoma cells." (PMID 40470716, 2025). "CALR is expressed in nearly all cells in the TME, IL1R1 is mainly expressed in tumor-associated fibroblasts and endothelial cells, and the expression levels of IFNG and IFNB1 are minimal, primarily by T lymphocytes." (PMID 40928500, 2025). "Expressing IFNB1 in MOC2 tumors suppressed tumor growth by attracting dendritic cells and T cells, and this effect was further amplified by co-expressing GM-CSF, which promotes immune cell development." (PMID 40282455, 2025). "In immunocompetent mice, IFNB1 expression suppressed MOC2 tumor growth by attracting DCs and T cells, an effect amplified by co-expressing the granulocyte–macrophage colony-stimulating factor." (PMID 40282455, 2025). "Compared to tumors derived from control MOC2 cells (80% parental MOC2 and 20% vector-transduced MOC2), tumors co-expressing IFNB1 and GM-CSF exhibited significantly inhibited growth, reduced tumor size, and decreased tumor weight." (PMID 40282455, 2025). "Therapy using liposomes carrying the IFNB1 gene led to the complete regression of tumor lesions in 1 out of 5 patients." (PMID 41373826, 2025). "Consistent with accumulation of nAlb at tumor sites, we found a notable increase in the expression of genes associated with STING pathway activation, including Ifnb1, Cxcl10, Cxcl9, and Tnfa." (PMID 38766114, 2024). "Radiation-induced anti-tumour immunity is mediated through cytosolic nucleic acid sensing pathways that drive the expression of interferon beta-1 (IFNB1) and proinflammatory cytokines." (PMID 39372406, 2024). "Radiation-induced activation of IFNB1, which is crucial for radiation-induced anti-tumour immunogenicity, can be a consequence of cytosolic dsDNA or dsRNA accumulation." (PMID 39372406, 2024). "Here we compared the effects of photon and proton therapy on the activation of anti-tumour immunogenicity markers including the nucleic acid sensing/IFNB1 axis and canonical NF-κB using multiple dose levels and a clinically relevant fractionation regimen." (PMID 39372406, 2024). "Intratumorally administered Alu-NPs elicited significantly increased gene expression of Ifnb1, Cxcl10, and Tnf in the tumor microenvironment (TME)." (PMID 37691856, 2023). "These RANO-treated tumours displayed increased expression of antigen presentation genes, as well as Ifnb1, Ifng and Cd274, indicating that RANO is effective in inducing an immunogenic phenotype in vivo." (PMID 37563469, 2023). "IFNB1, mediatinganti-tumor and anti-viral immune response, showed significant inhibitionin AEG-1-C75S hepatocytes compared to AEG-1-WT." (PMID 36548985, 2023). "The Ifne effects were distinct from those produced by Ifnb1, which inhibited primary tumor growth in both ΔS and ΔL tumors but was unable to efficiently suppress the metastasis of ΔL tumors." (PMID 36344707, 2022). "The six genes of the signature belonged to different functional immune-related groups: antigen presentation (HLA-DPA1 and CD1C), innate immune response (TLR7), type II interferon signaling (IFNB1), tumor marker (MMP2), and proliferation marker (MKI67)." (PMID 34209514, 2021).
tumor (continued). "Consistent with our in vitro studies, mice treated with free cGAMP showed rapid Ifnb1/Cxcl10 expression 6 h after intratumoural injection, while the activity decreased considerably over 48 h in both tumour and nodal tissues." (PMID 33558734, 2021). "The six genes belonged to different functional groups: antigen presentation (HLA-DPA1 and CD1C), innate immune response (TLR7), type II interferon signaling (IFNB1), tumor marker (MMP2), and proliferation marker (MKI67)." (PMID 34209514, 2021). "The life span of TANs is remarkably prolonged in tumor bearing Ifnb1(-/-) mice, compared to wild type controls." (PMID 31799175, 2019). "From these data, we conclude that the presence of circulating IFN-β in patients during neoadjuvant chemotherapy correlates with a longer DMFS, independently of IFNB1 expression levels and immune signatures in the tumor before therapy." (PMID 30546090, 2019). "TAMs from SNAIL1 depleted tumors displayed increased expression of M1-like/anti-tumor genes like Ifna1, Il12a, Il6, Nos2, and Ifnb1." (PMID 29593211, 2018). "Expression of CXCL1 and CXCL2 in blood and tumor was significantly higher in Ifnb1−/− mice as compared to wild-type (WT) controls." (PMID 28066438, 2016). "In Ifnb1−/− mice, considerably higher tumor growth was observed, accompanied by boosted angiogenic processes." (PMID 28066438, 2016). "Neutrophilic granulocytes from such Ifnb1−/− tumor-bearing mice expressed higher amounts of BCL-xL and showed decreased effector caspase 3 activity as well as inhibited expression of death receptor Fas." (PMID 28066438, 2016). "We next examined whether the observed tumor regression was dependent on adaptive immunity by inoculating the heterogeneous IFNB1/GM-CSF cell mixture into immunocompetent C57BL/6 mice and immunodeficient NSG mice." (PMID 40282455, 2025). "IFNB1 expression, further amplified by GM-CSF co-expression within tumors, could significantly counteract immune evasion and lead to effective tumor control." (PMID 40282455, 2025). "To evaluate whether the co-expression of IFNB1 and GM-CSF can control tumor growth independently of exogenous antigens such as SIINFEKL in MOC2SIIN, we assessed their effects in MOC2 tumors lacking both SIINFEKL and fluorescent protein expression." (PMID 40282455, 2025). "We found that the increased number of Ly6Clow macrophages in CD244fl/flLysMcre mice was accompanied by a significant upregulation of anti-tumorigenic macrophage markers and cytokines, including CD80, NOS2, IL6, and IFNB1, in CD11b+ sorted tumor-infiltrating macrophage populations." (PMID 38424542, 2024). "With this approach, we characterize single-cell production of Ifnb1, Xcl1 and Ccl5 in mouse tumors and identify monocytes and monocyte-derived macrophages as the main producers of type I interferon transcript Ifnb1 consistent across 4 different syngeneic tumor models." (PMID 39372774, 2024). "As IFNB1 has both direct antiangiogenic and anti-tumor effects, it can stimulate immune production." (PMID 38023241, 2023). "In addition, expression level of IFNA1 and IFNB1 increased with tumor grade in case of ER-positive BC, whereas it decreased in case of ER-negative BC." (PMID 35593921, 2022). "We observed that heat-iMVA in PRC2-loss murine tumor cells (AT3 [sgEed], SKP605 [sgEed]) not only triggered type I IFN production (e.g., Ifnb1 and Ifna4), but also rescued the PRC2-loss–mediated IFN-γ signaling deficiency, resulting in increased chemokines and Cd274 (Pdl1) expression." (PMID 35852856, 2022). "To confirm whether monocytes were indeed the source of IFNβ in the tumour microenvironment, we used B6.129-Ifnb1tm1Lky/J mice, which co-express IFNβ1 and eYFP from the Ifnb1 locus, bearing AE17 tumours." (PMID 35986006, 2022). "Ifnb1 has a potent inhibitory effect on tumor cell proliferation and immune regulation." (PMID 35646652, 2022). "In normal cells, IFNB1 produced in response to ribosome biogenesis may limit proliferation and serve to restrict tumor development." (PMID 31841110, 2019).